SHH (sonic hedgehog signaling molecule)
Diseases named in the same sentence as SHH in open-access papers (continued):
Sharing a sentence is not in itself a finding about the gene and the disease.
tumor (continued). "Che’s research reveals that activation of the SHH signaling pathway is positively correlated with tumor size, capsular invasion, and vascular permeation in HCC." (PMID 38730691, 2024). "In human tumour cells, inhibition of the SHH pathway reduces proliferation, highlighting its critical role in tumour growth." (PMID 39568072, 2024). "After treatment with vismodegib, a SHH signaling inhibitor, the Hes1-expressing tumor cells were changed from proliferative state to differentiated state." (PMID 38355808, 2024). "Studies on PTEN-deficient GBMs have shown that SHH and PI3K signalling pathways synergistically promote tumour growth and survival." (PMID 39568072, 2024). "This methodology reveals significant differences in tumor behavior based on SHH signaling status and provides a more comprehensive understanding of its role in EC." (PMID 39408773, 2024). "This approach reveals distinct differences in tumor behavior based on SHH signaling status, providing a clearer understanding of its role in EC." (PMID 39408773, 2024). "The Sonic Hedgehog (SHH) signaling pathway plays an essential role in self-renewal,tumor cell growth, drug resistance, metastasis, and recurrence of CSCs." (PMID 38985013, 2024). "Chromothripsis can cause SHH pathway gene amplification, such as GLI2 and MYCN, which increases SHH target gene expression and drives tumor development." (PMID 38391759, 2024). "Jeng reported that CD 133+ cells isolated from a mouse Hepa1-6-derived tumor showed a high expression of the components of the SHH signaling pathway." (PMID 38730691, 2024). "This confers increased activity to GLI1, thereby enhancing SHH signaling and sustaining cell proliferation and tumor onset." (PMID 38062245, 2024). "Sonic hedgehog (SHH), a ligand of Hedgehog (Hh) signaling by tumor cells is reported to drive immunosuppressive macrophage polarization from myeloid precursor cells and tumor development." (PMID 38703051, 2024). "We identified Dnmt1 as a druggable dependency in SHH-MB and show that DNMT1 inhibition can effectively inhibit tumor growth both in in vitro and in vivo models of SHH-MB by suppressing SHH signaling output." (PMID 39107797, 2024). "Within NBs, autocrine activation of the SHH pathway has been observed, where the tumour cells produce the SHH ligand themselves." (PMID 39568072, 2024). "The SHH pathway activated by H. pylori infection induces the expression of PD-L1 and the proliferation of tumor cells in GC, leading to the resistance to immunotherapy." (PMID 39434880, 2024). "Lentiviral-induced genetic depletion of SALL4 significantly suppresses tumor cell proliferation and correlates with the impairment of SHH signaling activity." (PMID 38062245, 2024). "The SHH signalling pathway plays a crucial role in cell differentiation and proliferation, such as in Rathke’s pouch, as well as in tumour cell migration." (PMID 39568072, 2024). "Inhibiting the SHH pathway in PDAC disrupts tumor growth and modifies the composition of CAFs, increasing inflammatory CAFs and decreasing myofibroblastic CAFs." (PMID 39335494, 2024). "Using the RCAS/tv-a system to target the expression of SHH, IGF2 and activated Akt to nestin-expressing neural precursors in mice, the researchers found that co-expression of SHH with IGF2 or Akt significantly increased tumour incidence." (PMID 39568072, 2024). "These in vivo data confirm the tumorigenic role of SALL4 in the regulation of SHH-dependent tumor growth." (PMID 38062245, 2024). "The trend of a linear decrease in the expression of SHH was observed with the progression of the tumour grade (p < 0.0001)." (PMID 37240278, 2023). "SHH-expressing cells in tumor tissue present in the bone marrow were observed when B16 cells had been inoculated into the tibial metaphysis." (PMID 37240209, 2023). "Despite all these frustrating facts, studies still prove the anti-tumor effects of SHH inhibitors in PDAC." (PMID 37784082, 2023).
tumor (continued). "While it was reported that SHH expression in low-HH-DLD-1 xenografts promotes neoangiogenesis by inducing tumor vascularity, tumors implanted in Hhip+ mice present higher angiogenesis." (PMID 37626893, 2023). "Using several murine tumor models, the authors showed that tumor cells secrete the ligand SHH, which is critical for TAM M2 polarization." (PMID 36674836, 2023). "In vivo, it was able to reduce the weight of HT-29 xenograft tumors, meanwhile the protein expression levels of SHH in TSN-treated tumor tissues were significantly lower than those in the control group." (PMID 36782251, 2023). "In vivo studies have shown similar results, with BRG1 required for SHH-target gene expression and tumour cell proliferation in mice." (PMID 37433987, 2023). "Nonetheless, OSCCs with overexpression of SHH presented PTCH-positive tumor blood vessels, which confirms that SHH signaling has autocrine and paracrine effects on neoangiogenesis." (PMID 37626893, 2023). "Specific genes and pathways, such as FOXA1 and Sonic hedgehog (SHH), have been shown to contribute to tumor metastasis." (PMID 36916531, 2023). "(2019), paradoxically, showed that SHH pathway inhibition in human ACPs led to a significant increase in tumor cell proliferation." (PMID 36748936, 2023). "In the last few years, Sonic-Hedgehog (SHH) signaling has been recognized as an important pathway for promoting tumor progression and by now it is widely recognized as a therapeutic target." (PMID 36836615, 2023). "SHH was highly expressed (31.9%) in grade 1 tumour, it being higher than all other grades and the control (p < 0.001–p < 0.0001)." (PMID 37240278, 2023). "The percentage of SHH-positive cells in Melan-A-positive tumor cells was significantly decreased in the GANT61-treated group (LI: 45 ± 5.08%) compared to the control group (LI: 65 ± 2.63%) (p < 0.05)." (PMID 37240209, 2023). "This was also confirmed by immunohistochemistry and suggests that the availability of SHH signaling peptide is greatly enhanced in vivo, thus rendering the tumor cells competent to receive a reverse paracrine signal." (PMID 37845394, 2023). "By way of example, a study by Rhim, Oberstein showed that reducing stromal desmoplasia in the TME of PDAC tumours (by inhibiting the SHH pathway component Smoothened) accelerated tumour growth and metastasis." (PMID 37190281, 2023). "Regarding the expressions of Gli1 and Gli2, we observed Gli1 and Gli2 expressions in the tumor tissue in the bone marrow in addition to SHH expression." (PMID 37240209, 2023). "Control G-SmoGli-luc mice showed an increasing BLI signal over time, reflecting cumulative tumor growth with SHH hyperactivation." (PMID 37333134, 2023). "The deregulation of SHH signaling is often observed during tumor formation and progression and is detrimental to the cancerous process." (PMID 36900220, 2023). "The SHH signaling pathway has been related to pituitary embryogenesis and seems to be involved in the maintenance of tumor stem cells." (PMID 36748936, 2023). "Two patients received long‐term TMZ chemotherapy before surgery, and mutations in the SHh (PTCH1) and PI3K/AKT signaling pathways (AKT1, PIK3CA, PTPN11) were detected in two tumor tissues (Patients 24 and 27)." (PMID 37533228, 2023). "BRG1 deletion in the cerebellum of mice led to decreased expression of SHH-target genes and reduced proliferation of tumour cells." (PMID 37433987, 2023). "SHH pathway was demonstrated to be directly or indirectly involved in tumor angiogenesis, and activation of Hh signaling in CAF can upregulate the expression of CXCR4 and IGF1R in TME." (PMID 37784082, 2023). "The top pathway in the non-tumor-specific sex-DMPs of SHH is YAP1- and WWTR1 (TAZ)-stimulated gene expression." (PMID 37035203, 2023). "Sonic hedgehog (SHH) is a hedgehog ligand that its secretion from tumour cells is contributed to the polarization of macrophages towards pro‐tumour TGF‐β high M2 phenotype, which further act for exclusion of CD8+ T cells." (PMID 36625080, 2023).
tumor (continued). "The overexpression of SHh contributes to excessive Hh signaling and is positively correlated with tumor burden in nearly all cancer types." (PMID 36517618, 2022). "In cancer, many stem cell pathways, such as Wnt, RAS, Sonic Hedgehog (SHH), and Notch, are overactivated, enabling tumor cells to possess EMT properties." (PMID 36613893, 2022). "SHH from tumor cells in turn induces expression of growth factors insulin growth factor 1 (IGF1) and growth arrest-specific 6 (GAS6) in PSCs." (PMID 35159011, 2022). "Sonic hedgehog (SHH) signaling plays a pivotal role in promoting oncogenesis, tumor growth and progression." (PMID 35831316, 2022). "Numerous preclinical studies have revealed that the combination of some chemicals with SHH inhibitorsresults in improved anti-tumor efficacy and survival in animal models." (PMID 36034794, 2022). "We identified that TYAs predominantly comprised of Group 4 (40%) and Sonic Hedgehog (SHH)-activated (33%) tumours, with Wingless-type (WNT, 17%) and Group 3 (10%) being less common." (PMID 35008416, 2022). "Treatments with inhibitors that target the upstream SHH signaling components, such as the SMO inhibitor vismodegib, cause an enrichment of tumor-associated astrocytic SOX2+ cells resulting in an increased chance of relapse." (PMID 36291792, 2022). "In particular, analysis of the hedgehog (HH) targets Gli1, MycN and Cyclin D2 proteins confirmed a similar SHH activity in the tumour samples of both backgrounds." (PMID 35839783, 2022). "In conclusion, it is considered that the best way to control the tumor recurrence is to evaluate and establish novel protocols combining SHH signaling inhibition with conventional therapies." (PMID 36010607, 2022). "Overall, a more pronounced expression of SHH was observed in tumor cells with low expression of DBP, and vice versa." (PMID 36014865, 2022). "In SHH-driven tumours, the knockdown of HHIP-AS1 induces mitotic spindle deregulation and the consequential reduction of tumorigenicity in vitro and in vivo." (PMID 36451206, 2022). "To analyse the expression of proteins of interest in the PDX model, we performed IHC staining for BMP2, BMP4, SMAD4 and SHH on tumor, lung and colon tissue 28 days post treatment." (PMID 35902550, 2022). "In contrast, full NbnKO impairs MB development both in SmoA1 mice and in an SHH‐driven tumour allograft." (PMID 35839783, 2022). "The analysis of gene expression patterns in the SHH subgroup showed up-regulation of cilium-related processes in TYAs, which is in line with the observation made with all MB tumours." (PMID 35008416, 2022). "Since KRAS mutations can lead to impaired mitochondrial respiration, this sophisticated reciprocal signaling node restores mitochondrial respiration in KRAS mutant tumor cells via SHH, IGF1R/AXL, and AKT." (PMID 36612058, 2022). "The body of evidence suggests that vitamin D inhibits the SHH signaling pathway and, therefore, displays a protective role in arresting tumor growth." (PMID 36014865, 2022). "A mouse model using CD133+ GBM cells showed that inhibition of Shh can delay GBM growth and promote apoptosis, while mice overexpressing SHH displayed faster tumor growth." (PMID 35954407, 2022). "Although the SHH pathway is inactivated in adult tissues under normal circumstances, dysregulation of the SHH signaling pathway closely links with tumor development and progression." (PMID 36034794, 2022). "The accumulating evidence suggests the ability of vitamin D to antagonize the Sonic Hedgehog (SHH) signaling, the key tumor pathway, and play a protective role in the development of BCC." (PMID 36014865, 2022).
tumor (continued). "Taken together, paracrine activation of fibroblast Hh pathway by SHH acts as a tumor suppressor to inhibit pancreatic tumor growth." (PMID 36010600, 2022). "In many tumor types, the SHH signaling pathway has been reported to crosstalk with other critical molecular signaling pathways involved in cancer, such as RAS/RAF/MEK/ERK, PI3K/AKT/mTOR, EGFR, and Notch." (PMID 36034794, 2022). "Consistent with this, the genetic or pharmacological inhibition of ERAP1 suppresses SHH-dependent tumor growth in vitro and in vivo." (PMID 35573667, 2022). "A crosstalk between SHH and PI3K-mTOR pathways was identified, which promoted tumor proliferation and survivability in PTEN-deficient glioblastomas." (PMID 36010600, 2022). "Since the discovery of the SHH pathway aberrates activation in cancers, the single-allele PTCH1-knockout mouse model has influenced our understanding of tumor development and is a valuable model that recaps the development of SHH-activated tumors." (PMID 36423085, 2022). "Upon merging data from six studies, SHH tumours were distributed across all age groups, whereas most Group 4 tumours (80%) were distributed between 4 and 15 years of age." (PMID 35008416, 2022). "Statins arrest SHH signaling in medulloblastoma cells and fibroblasts by inhibiting cholesterol synthesis, thus attenuating tumor proliferation." (PMID 34303383, 2021). "Activity of the tumor suppressor PTEN has been shown to influence phosphatidylinositol 3-kinase (PI3K) signaling, which then works in conjunction with SHH signaling to promote tumor growth and viability." (PMID 34012965, 2021). "Our results showed that treating mice with both SHH inhibitor Cyp and autophagy suppressor CQ markedly suppressed the tumor growth, compared with Cyp or CQ alone group." (PMID 34076346, 2021). "Similar to many embryonic signaling pathways in cancer, the SHH signaling pathway plays important roles in promoting oncogenesis and tumor growth and progression." (PMID 33906647, 2021). "PTCH1 and GLI1 mRNA expression as an indication of the canonical SHH signaling pathway activity in tumor malignancy." (PMID 33391411, 2021). "Two of them are associated with alteration in the Wingless (WNT) and Sonic Hedgehog (SHH) developmental signalling pathways (the WNT and SHH subgroups), while the other two are less well molecularly characterized and referred to as Group 3 and Group 4 tumours." (PMID 34302498, 2021). "In a study, exploiting a well-defined mouse model of PDAC, SHH was deleted and the resultant tumors were reported to be more aggressive, presenting undifferentiated histology with an increase of tumor angiogenesis, despite the reduction of the stromal volume." (PMID 34503252, 2021). "Because ACP, which is considered a benign tumor, carries a low rate of somatic mutations, mounting evidence suggests that the TGF-β, ERBB2 and SHH signaling pathways are involved in tumor formation in an autocrine or paracrine manner." (PMID 35155179, 2021). "Previous investigations, including our data, have supported that SHh is a useful biomarker for tumor metastasis, drug resistance and a target for tumor treatment." (PMID 33440657, 2021). "In vivo experiments were also conducted to validate the role of the LINC01426/SHH axis in LUAD tumor growth." (PMID 33568633, 2021). "In tumor cells, SHH signaling cascades are aberrantly activated by genetic alterations, such as loss-of-function alterations in PTCH1, gain-of-function mutations in SMO (T241M, L412F, S533N, W535L, and R562Q), and amplification of the GLI1 or GLI2 genes." (PMID 35048028, 2021). "As expected, we found that the SHH signaling pathway was overactivated in tumor cells especially in the progenitor-like tumor cells." (PMID 34210306, 2021). "The SHH subgroup comprises very heterogeneous tumours that share the overexpression of the SHH pathway." (PMID 34831165, 2021). "WNT and SHH are named because these tumours have mutations in the WNT and SHH signalling pathways, respectively." (PMID 34944941, 2021).
tumor (continued). "Significant overexpression of both GLI1 and GLI2 was found in intrahepatic CCC, when compared with non-tumor tissues (p < 0.001 and 0.05, respectively), suggesting a possible tumorigenic effect of SHH signaling during the development of CCC." (PMID 34948011, 2021). "Gene expression analyses of human embryonal tumor samples revealed similar gene expression patterns and significant overrepresentation of SHH and WNT target genes in both IO-MEPL and ETMR." (PMID 34785636, 2021). "One controversially discussed target is the SHH pathway, as it is known to be a pro-tumoral signaling pathway that regulates crosstalk between stromal and tumor cells." (PMID 34944807, 2021). "Taken together, our results suggested that simultaneous inhibition of the SHH signaling pathway and autophagy inhibited tumor growth in vivo." (PMID 34076346, 2021). "Aberrant activation of the sonic hedgehog (SHH) signaling pathway plays a vital role in tumor formation and development." (PMID 33546769, 2021). "The blockade of SHH protein secretion or the removal of astrocytes inhibits the formation of these tumoroids, suggesting that SHH signaling from astrocytes plays an important role in supporting tumor-growth." (PMID 34436033, 2021). "The findings above support that the SHH/GLI signaling pathway enables FAP to be involved in tumor growth and migration and the EMT process." (PMID 34068501, 2021). "Enhanced CCA migration was associated with induction in key EMT genes and several crucial EMT genes and inducers of EMT such as GLI, PTCHD1, SNAI1, SNAI2, and SHH, in tumor cells in response to inflamed LECs." (PMID 34831316, 2021). "Autophagy has been demonstrated to act as a key factor for the SHH signaling pathway functions, with marked effects on proliferation, apoptosis, and invasion of various types of cells, especially tumor cells." (PMID 34076346, 2021). "For example, SHH signaling represses autophagy to suppress tumor growth in stromal stellate cells by subduing autophagy‐induced alanine secretion." (PMID 34076346, 2021). "We found that the expression of both Gli1 and HDAC2 was significantly upregulated in SHH‐MB tumors compared to WT cerebellum, indicating the over activation of SHH signaling in SHH‐MB tumor cells." (PMID 34480519, 2021). "It is thus likely that SHH induced by KLF5KQ in tumor cells contributes to osteoclast differentiation by acting on osteoblasts to increase their release of IL-6." (PMID 33731701, 2021). "SHH pathway is also a key component of the autocrine and paracrine signalling promoting tumor progression, due to uncontrolled proliferation, sustained angiogenesis and invasiveness." (PMID 34439999, 2021). "The SHH-deficient tumor showed decreased stromal content, especially a-SMA-positive myofibroblasts, compared to the control tumor." (PMID 33614646, 2021). "Pharmacological suppression of the SHH signaling pathway led to dramatic inhibition of cell proliferation in vitro and tumor growth in vivo, proposing that HPI can be an effective and attractive molecular target therapy for human intrahepatic CCC." (PMID 34948011, 2021). "MM BM microenvironment is reported to have high levels of Hedgehog ligands, including SHH, which activates Hedgehog signaling in MΦs in MM tumor bed." (PMID 33993198, 2021). "It has been proven that SHH proteins regulate the formation of tumor microenvironment by activating the production of CAFs and myofibroblasts in the pancreas." (PMID 32414222, 2020). "The SHH signaling pathway activates in cancer stem cells of several neoplasms such as glioblastoma, as well as cancers of the colon, liver, breast, pancreas, and blood neoplasms (chronic myeloid leukemia and multiple myeloma)." (PMID 31979397, 2020). "During tumor development, SHH signaling has three major roles: driving tumor development, promoting tumor growth, and regulating residual cancer cells after therapy." (PMID 32957513, 2020).